APC (APC regulator of Wnt signaling pathway)
Diseases named in the same sentence as APC in open-access papers (continued):
Sharing a sentence is not in itself a finding about the gene and the disease.
tumor (continued). "NOTUM retains tumor suppressor activity in APC-ineffective adenomas." (PMID 38156313, 2023). "Furthermore, sex differences in APC have a significant impact on anti-tumour immunity and immunotherapy response." (PMID 36826068, 2023). "The genes with the most frequent SGMs associated with the three mutational processes are clearly enriched in core TSGs, including early oncogenic drivers such as APC, later drivers of tumor progression and metastasis such as CDH1, as well as less-characterized cancer genes such as EPHA2 and MGA." (PMID 37922356, 2023). "APC mutations often occur late in CAC progression, indicating it may be dispensable for tumor initiation for this unique subset of CRC." (PMID 37884500, 2023). "Finally, tumour epithelial AHCY expression was confirmed in APC and APC KRAS tumours and in human colon and CRC, with variation in expression between samples." (PMID 37580540, 2023). "Another ‘hit’ in the APC tumour suppressor, a Wnt pathway negative regulator altered in 20% of CIN GC, was concurrently engineered in C2 and C3 from D3 (referred to as D3C2 and D3C3, respectively) to examine the evolutionary consequence of dual tumour suppressor inactivation." (PMID 37258665, 2023). "Dual EP2/EP4 PGE2 receptor antagonists increased tumor microenvironment lymphocyte infiltration and significantly reduced disease burden in multiple tumor models, including in the adenomatous polyposis coli (APC)min+/− spontaneous colorectal tumor model, compared with celecoxib." (PMID 37559947, 2023). "Therefore, NSCLC plasma samples containing methylated APC were detected in around 20% of samples that presented tumor‐specific hypermethylation." (PMID 37901797, 2023). "Of the members of this signaling pathway, the APC, AXIN1, TCF7L2, and RHOA genes are most frequently mutated, the latter encoding a low-molecular-mass protein that contributes to cell invasiveness, adhesion, migration, and polarization, and tumor metastasis." (PMID 37509254, 2023). "The ApcMin/+ mouse harbours germline mutations in Apc that encode a truncated APC protein lacking any β-catenin binding capacity and typically gives rise to tumours in the distal small intestine." (PMID 37048063, 2023). "However, the effectiveness of focusing on upstream targets is still debatable due to tumor resistance with more downstream alterations, including CTNNB1- or APC-mutated malignancies." (PMID 37577746, 2023). "Adenomatous polyposis coli (APC) is a CRC tumor suppressor gene found on the 5q21-q22 chromosome." (PMID 38004598, 2023). "APC1 is a tumor suppressor of lncRNA, whose expression is stimulated by APC." (PMID 37280524, 2023). "The activity of cytoskeleton/APC/β-catenin/Oct4 signaling was examined in patient-derived tumor tissues with low, median, and high differentiation states, which were histologically graded based on hematoxylin and eosin (H&E) staining and biopsy observation according to Edmondson–Steiner grade." (PMID 37746658, 2023). "APC mutations were analyzed for association with TMB, Immune checkpoint molecules expression, CpG methylation level, Tumor purity (TP), Microsatellite instability (MSI) status and tumor-infiltrating lymphocyte (TIL)." (PMID 36977982, 2023). "Inactivation of the APC gene promotes tumor progression by increasing WNT/β-catenin signaling." (PMID 36831263, 2023).
tumor (continued). "Among the genomic biomarkers able to discriminate transformed tumours (hEMT, MES) from the epithelial state, we identified genes that have been previously linked with cell migration, invasion and EMT, such as RB1, VHL, ERBB2, ARHGAP26, PRDM1, APC." (PMID 36774358, 2023). "This indicated that APC mutation was tumor-site specific but not dependent of tumor grade and differentiation." (PMID 36645718, 2023). "The highly conserved central regions of γ- and ß-catenin facilitate their binding to various proteins, including the adenomatous polyposis coli (APC) tumor suppressor, T-cell factor/lymphoid enhancer factor (Tcf/Lef) transcription factors and axin/conductin proteins." (PMID 38069408, 2023). "APC likely mediates tumor suppressions by negatively regulating the Wnt/β-catenin pathway." (PMID 37407577, 2023). "Furthermore, monoallelic MLH1 methylation and APC promoter hypermethylation in tumour were observed in both MLH1 epimutation and germline MLH1: c.-11C > T carriers and MLH1 methylated EOCRCs." (PMID 37270516, 2023). "We have previously shown that the deubiquitinating enzyme USP7 is a tumor-specific WNT activator in APC-truncated cells by deubiquitinating and stabilizing β-catenin, but its role in gut tumorigenesis is unknown." (PMID 36669491, 2023). "Since the mechanics of cytoskeleton are crucial in multiple cellular functions, we thus hypothesize the existence of an intrinsic link between tumor cell mechanics and self-renewal via cytoskeleton–APC-mediated Wnt/β-catenin signaling." (PMID 37746658, 2023). "Our lab showed that the loss of Adenomatous Polyposis Coli (APC) caused an intrinsic resistance to doxorubicin (DOX), potentially through an enhanced tumor-initiating cell (TIC) population and the increased activation of STAT3 mediating the expression of MDR1 in the absence of WNT being activated." (PMID 37108784, 2023). "Preclinical studies provided evidence that taxanes show activity in CIMP-high cancers and colorectal tumors characterized by lack of mutations in the adenomatous polyposis coli (APC) gene, two related types of neoplasia." (PMID 35326652, 2022). "APC, a known tumor suppressor gene and key regulator of the Wnt signaling pathway, remains unknown in BTC." (PMID 36072793, 2022). "Loss of BCL9/9L accelerates differentiation and delayed tumour growth in APC or KRAS tumours." (PMID 35815339, 2022). "Then, these initiated cells rapidly expanded to form aberrant crypt foci and early adenoma, driven by mutations that cause hyperproliferation, such as APC mutations, or other signaling pathways such as WNT-β-catenin, cytokines, chemokines, and growth factors from the tumor microenvironment (TME)." (PMID 35463300, 2022). "To confirm these results, we knocked-down Pdk1 in APC; Sirt6IECΔ organoids and saw reduced organoid formation and growth, further supporting the involvement of glucose metabolism in Sirt6-driven tumor initiation." (PMID 35314684, 2022). "The comparison of whole-genome sequencing and whole-exome sequencing analyzes of Asian and Caucasian patients shows that there are substantial differences in the molecular tumor characteristics such as the alteration rate of important driver genes such as APC, ARID1A, PTEN and PIK3CA." (PMID 35326507, 2022).
tumor (continued). "Consistent with the presumed synergistic effect on mitotic exit, APC/C-inhibition alone or combined with a taxane can lead to strong mitotic cell death in certain tumor cells, but in others with high expression of the anti-apoptotic regulator Mcl-1, cell death is induced in interphase." (PMID 35832196, 2022). "Hypermethylation of multiple genes can occur simultaneously in a tumor, such as APC, DKPK1, MGMT, P16, and RASSF1 in lung cancer, while others, like RASSF1 and P16, could be hypermethylated in a variety of tumors." (PMID 37077808, 2022). "The predominantly metastatic tumours in our cohort contained more frequent mutations in several genes such as SETD2, APC, KDM5C, HIF1A, RBM10, TRAK1 and FBXW7, while we detected lower mutation rates in VHL compared to the primary tumours analysed in the TCGA study." (PMID 35231161, 2022). "Interestingly, combining an anti-RSPO3 antibody (OMP-131R10) with paclitaxel also reduced tumor growth and nuclear β-catenin expression in 8 APC mutant CRC PDX models when compared to monotherapy." (PMID 35204808, 2022). "Mutation co-occurrence analysis showed that no somatic mutations in other melanoma-associated genes were significantly correlated with APC/CTNNB1 somatic mutations after controlling for tumor mutation burden and multiple testing comparisons (data not shown)." (PMID 34986841, 2022). "Studies in APC-mutant mice found that decreased tumour burden upon IL-33-deficiency (but not IL-25-deficiency) is associated with reduced tumour mast cells, suggesting a potential pro-tumoral role downstream IL-33 signalling." (PMID 36263033, 2022). "In one tumor analyzed via WGS, two distinct SVs were found to affect the two APC alleles." (PMID 35343095, 2022). "Plasma miR-210 could stabilise carotid plaques by inhibiting adenomatous polyposis coli (APC), which is a well-known tumour suppressor gene with an inhibitory function in Wnt signalling, contributing to the balance between proliferation and apoptosis." (PMID 35563540, 2022). "APC is a tumor suppressor gene that is known to affect Wnt/β-catenin signaling and CD34 expression." (PMID 35887203, 2022). "While we could not delineate the sequence of mutations within a trunk of mutations, 2 of the 3 tumours had APC frameshift mutations at microsatellite regions, possibly hinting that APC inactivation came after MMR deficiency in the 2 tumours." (PMID 35581206, 2022). "The loss of APC leads to constitutive activation of the Wnt/β-catenin signaling pathway that sustains CSC survival and promotes the clonal exclusion of WT-ISC through the secretion of Wnt antagonists in the tumor microenvironment (TME)." (PMID 35053565, 2022). "Adenomatous polyposis coli (APC) gene is a tumor-suppressor gene on chromosome 5q21-q22." (PMID 36421339, 2022).
tumor (continued). "Tumor vaccines and adoptive T cell transfers have shown little efficacy and immune checkpoint inhibitor therapies are not efficacious in APC gene-mutation initiated, microsatellite-stable CRC." (PMID 35658010, 2022). "In this study, mutated APC and KRAS, which are supposed to occur in the early sequence of ACS, supports what Fearon stated about the importance of mutational sequence in determining tumor biologic behavior." (PMID 35709138, 2022). "Additionally, the ssGSEA algorithm compared 29 immune signatures and suggested that tumor-infiltrating cells, Tregs, checkpoints, inflammation-promoting cells, and APC, HLA, and IFN responses were highly active in cluster C1." (PMID 36618700, 2022). "On the other hand, in the C3PQ tumor model, we hypothesize that the function of APC was improved by an increase in DC and macrophage co-stimulating factors." (PMID 35356198, 2022). "To generate an experimental system with a more homogeneous and controlled APC defect, providing enough cells to analyze the underlying molecular and cellular mechanisms, we investigated the effects of silencing APC expression by small interfering RNA (siRNA) in CEM tumor T cells." (PMID 35417240, 2022). "Active GSK3β can act as a tumor suppressor as it participates, together with other members of the destruction complex including APC (Adenomatous Polyposis Coli), AXIN1 and CK1 (Casein Kinase 1), in phosphorylation and subsequent degradation of the oncogenic β-catenin protein." (PMID 34064046, 2021). "Indeed, chromosomal translocations that increase RSPO expression, or mutations that block ZNRF3/RNF43-mediated ubiquitination and degradation of FZDs, augment Wnt signalling in APC-proficient tumours that therefore, crucially, retain ligand-dependence." (PMID 33673710, 2021). "In addition, the Wnt signaling pathway is constitutively deactivated by the destruction complex, which is assembled around the tumor suppressors APC and Axin and targets β-catenin for destruction." (PMID 34829731, 2021). "Transcriptomic analysis of benign neurofibromas and MPNSTs from mouse models indicates that Wnt ligands have increased expression correlating with tumor progression, and components of the destruction complex of β-catenin are impaired most probably because APC and GSK3-β are downregulated." (PMID 34445326, 2021). "One of the main players in CRC is the tumor suppresser gene APC." (PMID 34571724, 2021). "However, both SPTAN1 and APC, which were significantly associated with response, and PARP4, which was mutated in chemosensitive tumours only, have been described as DDR-involved genes." (PMID 34934968, 2021).
tumor (continued). "APC plays a principal role in CRC development as a tumor suppressor gene." (PMID 34584977, 2021). "We did not see any significant differences in the distribution of APC mutations among different age groups or between left- and right-sided primary tumor sites." (PMID 35141142, 2021). "APC is a well-known tumour suppressor gene and this finding is in agreement with previous reports." (PMID 33461604, 2021). "APC truncation or post-irradiation depletion of Lgr5+ ISCs induces radioresistant Krt19+Lgr5− upper-crypt progenitors to dedifferentiate, via an Lgr5+ state, spawning tumours both in the small intestine and colon." (PMID 33673710, 2021). "Yet, remarkably, restoring APC function to shApcKrasG12Dp53R172H/− invasive carcinoma models suffices to induce cell differentiation, restore niche homeostasis, and elicit tumour regression, attesting to the therapeutic potential of targeting the Wnt pathway in CRC." (PMID 33673710, 2021). "APC is a tumor-suppressor gene that plays a key role in the earliest step of CRC carcinogenesis." (PMID 33919924, 2021). "As for the tumor counterpart, tissue derived from P12 harbored a PIK3CA missense mutation (chr3_178928067_C_A), two APC stop-gain mutations (chr5_112173917_C_T; chr5_112175951_ G_T), a PTEN stop-gain mutation (chr10_8972066_8972078dup), and a KRAS missense mutation (chr12:_25398284_C_A)." (PMID 34154611, 2021). "APC was originally considered to target β-catenin for degradation and act as a tumor suppressor." (PMID 35054411, 2021). "APC is a tumor suppressor with a functional role in the canonical Wnt/β-catenin signaling pathway." (PMID 34202548, 2021). "On the other hand, dietary iron (in excess) can enhance tumor formation in mice harboring abnormalities in Adenomatous polyposis coli (APC) whereas iron chelation could hinder tumor development." (PMID 33737539, 2021). "A high deletion rate in chromosome 5q22.2 may explain poor clinical outcomes in young CRC patients, which is because the region contains several tumor suppressor genes, such as APC and MCC." (PMID 34702313, 2021). "Moreover, the type A receptor of IL-17 stimulates ERK, p38 MAPK, and NF-κB signaling and induces the proliferation of transformed enterocytes that lack APC tumor suppressor functions." (PMID 34950252, 2021).